HUS1 (HUS1 checkpoint clamp component)
Description:
Component of the 9-1-1 cell-cycle checkpoint response complex that plays a major role in DNA repair. The 9-1-1 complex is recruited to DNA lesion upon damage by the RAD17-replication factor C (RFC) clamp loader complex. Acts then as a sliding clamp platform on DNA for several proteins involved in long-patch base excision repair (LP-BER). The 9-1-1 complex stimulates DNA polymerase beta (POLB) activity by increasing its affinity for the 3'-OH end of the primer-template and stabilizes POLB to those sites where LP-BER proceeds; endonuclease FEN1 cleavage activity on substrates with double, nick, or gap flaps of distinct sequences and lengths; and DNA ligase I (LIG1) on long-patch base excision repair substrates. The 9-1-1 complex is necessary for the recruitment of RHNO1 to sites of double-stranded breaks (DSB) occurring during the S phase.
Synonyms: hHUS1
Tractability: Small molecule: a structure with a bound ligand is known. PROTAC: ubiquitination databases record sites on it.
Gene: Protein-coding gene on chromosome 7 (47,961,882 to 47,979,682, reverse strand). Ensembl gene ENSG00000136273.
Subcellular location: Nucleus; Cytoplasm, cytosol
Subcellular location (Human Protein Atlas): Nucleoplasm
Pathways (Reactome):
DNA Repair: HDR through Single Strand Annealing (SSA); Presynaptic phase of homologous DNA pairing and strand exchange; Processing of DNA double-strand break ends
Cell Cycle: Activation of ATR in response to replication stress; G2/M DNA damage checkpoint
Disease: Impaired BRCA2 binding to RAD51
Gene Ontology:
Molecular function: protein binding
Biological process: cellular response to ionizing radiation; DNA damage checkpoint signaling; DNA damage response; DNA repair; double-strand break repair via homologous recombination; meiotic DNA integrity checkpoint signaling; mitotic DNA replication checkpoint signaling; mitotic intra-S DNA damage checkpoint signaling; nucleotide-excision repair; telomere maintenance; embryo development ending in birth or egg hatching; response to radiation
Cellular component: checkpoint clamp complex; nucleoplasm; nucleus; site of double-strand break; cytosol; nucleolus
Genetic constraint (gnomAD): Loss-of-function variants: 21 observed, 20.46 expected, observed/expected ratio (o/e) 1.03, 90% interval 0.73 to 1.48. The upper end of that interval is the gene's LOEUF score, 1.48, which puts it in group 6 of 6, group 1 being the genes least tolerant of losing a copy. Missense variants: 231 observed, 233.88 expected, observed/expected ratio (o/e) 0.99, 90% interval 0.89 to 1.1. Synonymous variants: 86 observed, 84.57 expected, observed/expected ratio (o/e) 1.02, 90% interval 0.85 to 1.22.
Homologues: Orthologues: chimpanzee HUS1 (100% identical), pig HUS1 (90% identical), rat Hus1 (86% identical), mouse Hus1 (86% identical), guinea pig HUS1 (84% identical), dog HUS1 (79% identical), rabbit HUS1 (79% identical), dog HUS1 (78% identical), tropical clawed frog hus1 (68% identical), zebrafish HUS1 (65% identical), Drosophila melanogaster Hus1-like (31% identical), Caenorhabditis elegans hus-1 (31% identical). Paralogues in human: HUS1B (49% identical).
Diseases named in the same sentence as HUS1 in open-access papers:
HUS1 is named in the same sentence as 19 diseases in open-access papers, as found by Europe PMC text mining. Sharing a sentence is not in itself a finding about the gene and the disease. The quoted sentences say what the papers report.
hepatocellular carcinoma (3 papers, 2020 to 2022). A malignant tumor that arises from hepatocytes. "This is different to previous results in hepatocellular carcinoma in which HUS1 was demonstrated to act as a tumor suppressor, as evidenced in experiments assessing cell proliferation and colony formation assays and migration and invasion assays." (PMID 35456300, 2022). "HUS1 can act as a potential tumor suppressor of hepatocellular carcinoma." (PMID 34173014, 2022). "Previous study shows that HUS1 is a potential tumor suppressor in primary hepatocellular carcinoma." (PMID 33137086, 2020).
lung carcinoma (3 papers, 2020 to 2023). "Contrarily, antisense oligonucleotides that inhibit HUS1 increase the sensitivity of human lung carcinoma cells to the chemotherapy drug cisplatin, and high HUS1 expression is significantly associated with unfavorable clinicopathologic indicators in ovarian cancer." (PMID 37222810, 2023). "On the contrary, downregulation of HUS1 by antisense oligonucleotides enhances the sensitivity of human lung carcinoma cells to cisplatin and high HUS1 expression is significantly correlated with poor prognostic clinicopathologic factors in ovarian cancer." (PMID 33137086, 2020). "We further show that knockout of HUS1 in KP model clearly inhibits lung cancer malignant progression." (PMID 33137086, 2020). "Nonetheless, clinical analyses show that HUS1 is inversely correlated with miR-190b expression in Chinese human lung cancer." (PMID 33137086, 2020). "It was shown that, in lung cancer, HUS1 promotes the ability of cells to proliferate or migrate." (PMID 35456300, 2022). "Such a situation has been described in lung cancer, in which HUS1 is targeted by MiR-340-3p." (PMID 35456300, 2022). "Interestingly, HUS1 expression was frequently up-regulated in Chinese lung cancer samples compared to adjacent pathologically normal lung tissues." (PMID 33137086, 2020). "Additionally, HUS1 is highly expressed in lung cancer and also gains gene copy numbers." (PMID 33137086, 2020). "Almost no lung cancer was visible when HUS1 was knocked out." (PMID 33137086, 2020).
ovarian carcinoma (3 papers, 2020 to 2023). A malignant neoplasm originating from the surface ovarian epithelium. "In addition, HUS1 expression was defined as a poor prognostic parameter for ovarian cancer." (PMID 35456300, 2022).
anemia (1 paper, 2015). A reduction in the number of red blood cells, the amount of hemoglobin, and/or the volume of packed red blood cells. "CYP2C8 rs11572076 was associated with the risk of anemia (HR 3.4 [95% CI 1.7–6.20], p = 00037), as was IL12A rs568408 (HR 1.98 [95% CI 1.39–2.82], p = 0.00014) and HUS1 rs2037483 (HR 0.54 [95% CI 0.39–0.74], p = 0.00016)." (PMID 25741362, 2015).
asthma (1 paper, 2022). "Therefore, these genes can increase the odds and show an up-regulated effect on the outcome of asthma, while 40 genes including CNBP, POLL, ZNF696, HUS1 among others impose a down-regulated effect on the disease response." (PMID 35606385, 2022).
bladder cancer (1 paper, 2022). "When analyzing the sequence of interest in detail, 7p12.2–p11.2 prioritized genes that had not previously been reported as regulators of platinum-based chemotherapy responses in bladder cancer including HUS1, ABCA13, IKZF1, EGFR, and FIGNL1." (PMID 35456300, 2022). "In line with our preliminary results, TCGA (The Cancer Genome Atlas) database provides the first evidence that mRNA expression of HUS1 is a statistically significant prognostic parameter of poor survival in bladder cancer patients." (PMID 35456300, 2022).
germinoma (1 paper, 2010). A malignant germ cell tumor arising in the central nervous system. "Genes CHEK2 and HUS1, which are involved in the DNA damage checkpoint, were significantly overexpressed in germinomas (p = 3.45*10e-2)." (PMID 20178649, 2010).
glioma (1 paper, 2023). A benign or malignant brain and spinal cord tumor that arises from glial cells (astrocytes, oligodendrocytes, ependymal cells). "Moreover, the gene expression level analysis by RT-qPCR suggested that among 10 DDR-related signature genes, HUS1, NUDT1, GADD45G, APEX1 and FAM175A were highly expressed in patients with glioma." (PMID 37086071, 2023).
lung adenocarcinoma (1 paper, 2022). A carcinoma that arises from the lung and is characterized by the presence of malignant glandular epithelial cells. "The research team from China Medical University declared that the miR-340-3p-HUS1 axis inhibited the proliferation and migration of lung adenocarcinoma cells." (PMID 35813473, 2022).
xeroderma pigmentosum (1 paper, 2022). Xeroderma pigmentosum (XP) is a rare genodermatosis characterized by extreme sensitivity to ultraviolet (UV)-induced changes in the skin and eyes, and multiple skin cancers. "In fact, HUS1 gene is one of the top associated genes with Xeroderma pigmentosum, since it is responsible for the impaired repair capacity of UV-mediated DNA damages." (PMID 36437479, 2022).
Zika virus infection (1 paper, 2017). "As Zika virus infection enhanced HUS1 mRNA significantly, we next examined for DDR markers." (PMID 29022904, 2017).
tumor (9 papers, 2011 to 2025). "Downregulation was observed for the genes CCNG2 (−9.0-fold), CCND1 (−5.84-fold), TFDP1 (−5.84-fold), CDC34 (−5.14-fold), and HUS1 (−4.52-fold), which are normally linked to the development of various tumor types when overexpressed." (PMID 39337305, 2024). "This chromosomal deletion causes the haploinsufficiency of several key tumor suppressors located on chromosome 7, such as EZH2, PMS2, HUS1, and NAMPT." (PMID 40981111, 2025). "When comparing the 28 significant genes in ER+ tumor tissues and the 9 significant genes in ER+ adjacent normal tissues, 2 genes overlapped (HUS1 and PRKAG3)." (PMID 38886818, 2024). "Statistical analyses of the tumor burden, number and area further supported the essential role of HUS1 in lung tumorigenesis." (PMID 33137086, 2020). "Pathological analyses uncovered a drastic inhibition of tumor formation by HUS1 knockout in KP model." (PMID 33137086, 2020). "We identified three tumor suppressors including miR30b, miR146a and miR-190b, and further showed that miR-190b inhibited lung tumorigenesis potentially through targeting the HUS1 gene." (PMID 33137086, 2020). "As a result, HUS1's potential function as a tumor promoter or a tumor suppressor may depend on the kind of malignancy and be organ-specific." (PMID 37222810, 2023). "On the other hand, HUS1, when acting as an oncogene, may be a target for tumor-suppressive miRNA." (PMID 35456300, 2022). "Thus, the potential role of HUS1 as a tumor suppressor or tumor promoter may be organ-specific and varies with the types of malignancy." (PMID 33137086, 2020).
cancer (4 papers, 2020 to 2026). A tumor composed of atypical neoplastic, often pleomorphic cells that invade other tissues. "Knockdown of HUS1 in hGBMs strongly reduced cell viability in accordance with data from Cancer Dependency Maps (precluding further experiments using Hus1 knockdown vectors)." (PMID 39053460, 2024). "In vivo data argue that a targeted inhibition of the 9-1-1 complex such as with HUS1 may be an effective strategy for the treatment of ATM-deficient and other cancers." (PMID 35456300, 2022). "The potential regulation of HUS1 by miR-190b was further supported by the negative correlation in Chinese clinical cancer samples, but not in the TCGA database." (PMID 33137086, 2020).
infection (2 papers, 2018 to 2020). The state of being infected such as from the introduction of a foreign agent such as serum, vaccine, antigenic substance or organism. "It is possible that, when faced with chronic replication stress within the host cell, HUS1 safeguards genomic variability, increasing survival and ensuring successful infection." (PMID 30380080, 2018). "Also, the broader implications of this divergent role of HUS1, especially in the context of infection, need to be further explored." (PMID 30380080, 2018). "However, due to the difficulty in viral packaging and infection, we failed to perform double knockouts of the miR-190b and Hus1 in KP model, which requires three guide RNAs." (PMID 33137086, 2020).
HUS1 also shares sentences with these, for which no sentence is quoted: breast carcinoma (1 paper); cervical carcinoma (1); Fanconi Anaemia (1); prostate carcinoma (1); Telangiectasia (1).